IL6 (interleukin 6)
Diseases named in the same sentence as IL6 in open-access papers (continued):
Sharing a sentence is not in itself a finding about the gene and the disease.
tumor (continued). "The other probable contributor to the elevated Snail in OSF is IL-6 since IL-6 has been shown to induce Snail expression in tumor cells and promote metastasis, and our results showed that the expression of Snail was indeed affected by IL-6." (PMID 32570756, 2020). "We found that ERO1L promoted the secretion of the classic tumor marker CA125 through the IL6 signaling pathway and formed a positive feedback pathway." (PMID 33056994, 2020). "PTHrP can also directly induce OC differentiation and maturation by promoting secretion of IL-8, IL-6, IL-11, and other OC differentiation factors by tumor cells." (PMID 32269963, 2020). "Sixth, MDSCs attenuate the development of tumor antigen-specific effector T-helper cells (Th1) through IL-6 production." (PMID 32942545, 2020). "To date, various signaling pathways, including PGE2, CCL2, CSF-1, TGF-β, CXCL5, CXCL12, IL-1β, and IL-6, have been identified to be involved in the infiltration and activation of MDSCs in tumor microenvironment." (PMID 32824865, 2020). "Other studies demonstrated that tumor spread is also sustained by the overexpression of IL-6, which in turn leads to the upregulation of matrix-metalloproteinases, adhesion molecules and endothelial leukocyte adhesion molecules." (PMID 32211076, 2020). "Their contribution includes the formation of an immunosuppressive tissue microenvironment, e.g., through interleukin 6 (IL-6)-dependent stimulation of suppressive myeloid cells, and their ability to restrict anti-tumor T cell reactions." (PMID 31414165, 2020). "Cytokines such as IL6 and TNFa can enhance the endothelium adhesion activity by promoting adhesion molecules’ expression on tumor vessels." (PMID 33381115, 2020). "We also show that the secreted lactate as a result of metabolic reprogramming in response to stromal IL6 remodels the tumor immune microenvironment to make it immune evasive, by favoring M2 macrophages in the microenvironment." (PMID 33177492, 2020). "By suppressing STAT3 phosphorylation, STAT3 activation is reduced, IL-6 production decreases, thus inhibiting tumor growth and ovarian metastases." (PMID 33536913, 2020). "TAMs polarize towards M2 type through the IL-6/STAT3 signaling pathway to promote tumor metastasis and rejects immune cells from penetrating." (PMID 33537237, 2020). "The fact that IL-6 exerts a bivalent action is one of the most controversial aspects of the role of the immune system in the tumor microenvironment of advanced ovarian cancer, as demonstrated in our previous papers." (PMID 32269279, 2020). "Through the STAT3 pathway, exogenous IL-6 induces the secretion of tumour-derived IL-6 to create a microenvironment that is favourable for the metastasis of CRC cells." (PMID 32760201, 2020). "Since these miRNAs target IL-6, they are tumor suppressors and therefore down-regulated in Tr-R cells, compared to control cells." (PMID 32483313, 2020). "Based on the results from proteome profiler, NLC-Citral reduced the level of IL-6 and IL-1α expression in the 4T1 tumor." (PMID 32526880, 2020). "The decreased LGR5, β-catenin, mTOR, and IL-6 levels, and increased miR-142-3p level in tumor samples collected from mice that received MSI-N1014, support our proposed anti-CRC mechanism of action." (PMID 32560222, 2020). "In these co-cultures of tumour cells and monocytes, we detected upregulation of cytokines (TNFα, MCP-1, IL-10, CXCL-10, IL-1β, IL-6, IL-23) associated with MOv18 IgE ADCC compared to isotype control-triggered cytotoxicity." (PMID 33203088, 2020). "In general, CAR-T cells would kill tumor cells accompanied with the release of cytokines, including IL-2, IL-4, IL-6, IFNγ, and TNFα." (PMID 31998790, 2020). "It is well known that IL-6 plays a crucial role in the stimulation of inflammatory cytokine production, tumor angiogenesis, cell proliferation, and tumor macrophage infiltration." (PMID 33266317, 2020).
tumor (continued). "Previous reports have indicated the IL-6 as a crucial player in mobilizing anti-tumor T cell immune response, and in the activation, proliferation and survival of lymphocytes during active immune responses." (PMID 32370100, 2020). "Tumor-derived TLR2 ligands were shown to be critical for the generation of immunosuppressive IL-6- and IL-10-producing DCs." (PMID 32486257, 2020). "We used a cytokine array to find the difference in cytokine secretion between control and tumor conditional medium treated macrophages, and the result indicated that IL-6 and INF-γ were the most variable of all cytokines." (PMID 32581055, 2020). "As a result, there is an increased infiltration of cells of the immune system in affected tissues, especially in adipose tissue and skeletal muscle, and consequent release of tumor secreted products, mainly TNFα and IL-6, among others." (PMID 33613297, 2020). "The activation of neutrophils that produce IL-1β which leads to dendritic and macrophage produce IL-6, a cytokine that acts as a tumor promoter." (PMID 33369455, 2020). "Among tumor-promoting cytokines (Gro-α, IL-6 and IL-8), IL-6 was remarkably increased by AN in IHOK." (PMID 32856877, 2020). "Meanwhile, the levels of proinflammatory cytokines (tumor necrosis factor (TNF)-α, interleukin (IL)-β, IL-1α, and IL-6) were also increased, indicating the formation of a beneficial inflamed tumor microenvironment." (PMID 32111828, 2020). "These mice contained low levels of IL-23 and upregulated IL-17A in the colon mucosa; tumor formation and intratumoral IL-23 expression were observed to be restored in environments with overexpression of IL-6." (PMID 32357539, 2020). "An analysis of the secretion of cytokines from these cells showed a similar increase in IL6 and TNFα as the tumor progressed." (PMID 33177492, 2020). "A limit of this study is that the systemic IL-17 levels were not directly analyzed and the authors instead showed the Th17 cells differentiation-related cytokines IL-23, IL-1β, and IL-6 in the local tumor tissue." (PMID 32298379, 2020). "Taken together, these data indicate that atorvastatin can induce atypical cellular senescence in HCC cells to inhibit tumor growth, an effect mediated by downregulation of hTERT through suppression of the IL-6/STAT3 pathway." (PMID 32257389, 2020). "In Walker-256 tumor-bearing rats increased systemic inflammation was observed with animals presenting elevated plasma TNF-α and IL-6 compared to non-tumor-bearing control animals." (PMID 33329046, 2020). "An IL-8-neutralizing antibody and an anti-CCN2 neutralizing antibody which lead to reduced IL-6 production have both shown therapeutic potential in suppressing tumor progression of HCC in vitro and in vivo with a xenograft murine model." (PMID 32850829, 2020). "It has been shown that the tumor microenvironment is enriched with various soluble mediators, including IL-6, TGFβ, IL-1β, and IL-23, which collectively promote Th17 differentiation via induction of master transcription factor RORγ5,6." (PMID 32770025, 2020). "In PDAC patients, increased IL-6 serum levels have been correlated with tumor size and the presence of liver metastases." (PMID 32865617, 2020). "In cholangiocarcinoma, a high expression of the oncoprotein, gankirin, promotes tumor proliferation, invasion and metastasis through the activation of the IL-6/STAT3 signaling pathway." (PMID 32283655, 2020). "We found that that IL6 was substantially expressed compared to IL10 in H. pylori-infected tumor tissues." (PMID 33569347, 2020). "Combination with anti–CTLA-4 led to tumor regression accompanied by enhanced T cell activity, increase in activated CD86+ monocytes in the tumor, augmentation of pro-inflammatory IFNγ, TNFα, and IL-6 and decrease in immunosuppressive MCP-1 and IL-10 cytokines." (PMID 32793228, 2020).
tumor (continued). "To investigate the effect of HO-1 on tumor-related inflammation, we measured the concentration of IL-6, IL-10, IL-12, MCP-1 and IFNγ in serum using the BDTM CBA Mouse Inflammation kit." (PMID 33287312, 2020). "The macrophages in tumor tissues generally have M2 phenotype induced by tumor-derived soluble factors such as GM-CSF and IL-6." (PMID 33343575, 2020). "Firstly, through the release of TGF-β and IL-6, CAFs suppress the proliferation and trafficking capacity of antigen-presenting DCs, thereby interfering with tumor-directed T cell priming." (PMID 32290124, 2020). "In contrast to the presence of infiltrating F4/80-positive macrophages and the elevated expression of F4/80 and Ly6c, the mRNA expression of TNFα, IL-6, Il-1β, and IL-17 were paradoxically downregulated in the tumor-bearing 12-month-old Atg7ΔHep livers." (PMID 32382012, 2020). "Tumor cells have been known to exploit IL-6 to evade apoptosis by acquiring drug resistance through activation of pro-survival oncogenic pathways." (PMID 33279931, 2020). "In particular, we focused on genes associated with cytotoxic lymphocyte phenotype and function (CD3, CD8, Interferon-γ, Granzyme B, Perforin, and IL-2 receptor B/CD122) as well as IL-6 and IL-6 receptor given our serum ELISA and tumor PCR results for IL-6." (PMID 32084139, 2020). "The best described mechanism under which IL-6 increases tumor invasion is by conferring tumor cells on an EMT phenotype, through which tumor cells transit from adherent epithelial to mobile mesenchymal states thus facilitating invasion and metastasis." (PMID 32855767, 2020). "In melanoma cells, both IL-1α and IL-1β can promote tumor angiogenesis by activating NF-κB signaling pathways to induce the expression of IL-6, IL-8, intercellular adhesion molecule-1, and tissue factor." (PMID 32993787, 2020). "IL-6 has been shown to increase metastatic capability in a variety of tumor models by multiple mechanisms." (PMID 32855767, 2020). "Together, this shows that disrupting activin A signalling in the tumour decreases systemic abundance of tumour‐derived IL‐6 and coincides with reversal of cachexia in the mice." (PMID 31436048, 2020). "When the tumor was resected, all of these symptoms disappeared and when these tumor cells were cultured in vitro, IL-6 was released into the culture medium." (PMID 32743515, 2020). "In prostate cancer, miR-205 inhibits tumor-driven fibroblast activation by reducing the secretion of proinflammatory cytokines such as IL-6." (PMID 33213510, 2020). "Since several lines of evidence have shown that IL6 and STAT are involved in tumor metastasis in some types of cancers, we asked if IL6 relies on STAT for renal cell metastasis." (PMID 31636361, 2020). "In this study, we evaluated the role of STAT3 and IL-6 in a tumor microenvironment mediated drug resistance in human MBs." (PMID 33279931, 2020). "IL-6/JAK2/STAT3 signaling can down-modulate the antitumor immunity of tumor-infiltrating immune cells because STAT3 negatively regulates the functions of neutrophils, natural killer (NK) cells, effector T cells, and dendritic cells." (PMID 32883032, 2020). "IL-6 has long been considered a mediator of tumor cell proliferation by binding to IL-6 receptors (IL-6R)." (PMID 33224886, 2020). "Other molecules have been reported in cancer that can influence tumor growth through regulation of the IL-6/STAT3 signaling pathway." (PMID 32283655, 2020). "Beyond the ability to promote the release of proinflammatory molecules such as IL-1β and IL-6 in the tumor microenvironment, estrogens and IIGFs-mediated signals have been shown to cross-communicate with certain adipokines such as leptin." (PMID 33364239, 2020). "After incubation with IL-6, the total concentration of the EpCam+CD44hiCD24– and EpCam+CD44hiCD24low cells decreased, and the concentration of the EpCam+CD44lowCD24– tumor cells drastically increased (2.3 times), i." (PMID 32523653, 2020).
tumor (continued). "Low levels of IL-1β, TNF-α, and IL-6 stimulate angiogenesis, and IL-6 modulates polarization of tumor-associated macrophages (TAM) from M1 (a tumor-eliminating phenotype) to M2 (an anti-inflammatory and tumor-promoting phenotype)." (PMID 33195486, 2020). "The activation of NF‐κB leads to cytokine production, especially IL‐6, IL‐11 and IL‐22, providing an inflammatory environment for the growth of premalignant tumours." (PMID 32347623, 2020). "Recent evidence suggested that platelets can release platelet-derived growth factors and pro-angiogenic protein (such as interleukin-6) and act as chemoattractants to promote growth, migration and angiogensis of tumor cells." (PMID 32742472, 2020). "Hepatocarcinoma frequently arises in an inflammatory tumor microenvironment where interleukin-6 (IL6) is a critical mediator of HCC development through its trans-signaling pathway." (PMID 33316927, 2020). "It was noted that in the KrasG12D model, the massive activation of the STAT3 pathway, which led to tumour progression, was induced by tumour-infiltrating myeloid cells, which stimulated the neoplastic cells via IL-6 trans-signalling." (PMID 32864098, 2020). "One study demonstrated that IL6 signaling activated by systemic thermal therapy in a mouse model with the ovalbumin-expressing B16 tumor significantly upregulated E/P-selectin and ICAM1, which enhanced the CD8+ T-cell trafficking." (PMID 33381115, 2020). "IL-6 is known to stimulate tumor infiltration by macrophages in ovarian tissue, and this phenomenon is associated with worse prognosis of OC patients." (PMID 33062717, 2020). "The activated TLRs can elicit an inflammatory response in the region of the tumour via interleukins such as IL-23, IL-17, IL-18, and IL-6." (PMID 32370077, 2020). "Mechanistically, hypoxia and IL-6 can promote the m2-like phenotype deflection of the tumor from M1-to enhance the metastasis of LLC." (PMID 33224886, 2020). "The EMT can be induced by several of numerous pleiotropic growth factors or cytokines (EGF, HGF, FGF, TGF-β, NOTCH, IL-6, IL-8, among others) that can be produced by different cells present in the tumor." (PMID 32478091, 2020). "IL-6 expression increased with tumor grade; however, while close to setup p value, this measurement was not statistically relevant." (PMID 32156252, 2020). "Although monocyte is the major source for IL-6, it can be produced by many cells including dendritic cells, lymphocytes, neutrophils, mast cells, mesenchymal and stromal cells, glial cells, and tumor cells." (PMID 32046104, 2020). "Another key pro-inflammatory cytokine is IL-6 and the anti-tumor impact of its inhibition has been extensively studied in vivo in combination with both chemotherapy and immunotherapy with an anti-PD1 agent." (PMID 32659999, 2020). "Based on previous studies in hepatocytes and a tumor cell line, proinflammatory cytokines IL-6 and TNF-α are involved in regulation of CYP1B1 expression." (PMID 32260461, 2020). "IL-6 mediated cross-talk between CAFs and cancer cells not only by promoting tumor cell proliferation, but also by promoting fibroblast activation." (PMID 32637576, 2020). "Active tumor cells will produce even more IL-6, promoting the tumor environment with inflammatory mediators that support tumor growth and metastasis." (PMID 33536913, 2020). "IL-6 also causes resistance to chemotherapy, a process strongly linked to CSC enrichment, in different tumor types, including renal and ovarian carcinomas." (PMID 32120774, 2020). "This NK cell infiltration in the tumor tissue was proposed to be induced by the enhanced IL-6 release after physical activity." (PMID 32231659, 2020). "Extracellular IL-6 binds to the cell surface receptor glycoprotein 130 (gp130), thereby activating signaling pathways that promote inflammation, immune reaction, and tumor progression." (PMID 31979221, 2020).
tumor (continued). "IL-6 is considered a tumor biomarker, and blocking the IL-6 signaling pathway is considered a therapeutic approach in HCC25–27." (PMID 32257389, 2020). "In contrast, iCAFs are located further from cancer cells and are recognized by their high expression of tumor-promoting cytokines and chemokines such as interleukin-6 (IL-6)." (PMID 33213510, 2020). "Data obtained in our model are consistent with other reports presenting IL-6 KO mouse constructs and various roles of IL-6 in behavior, systemic inflammation, and most importantly, in the course of inflammation-related local tumor induction." (PMID 32867390, 2020). "Neutrophils can exert tumor-promoting activity by secreting a variety of inflammatory mediators, including vascular endothelial growth factor, interleukin (IL)-6, IL-10, and IL-22." (PMID 32528232, 2020). "The STAT-3 signaling pathway plays a prominent role in diverse cellular behaviors mediated by IL-6, including tumor cell survival, invasion, and metastasis." (PMID 32855767, 2020). "Tumor cells first increase and activate platelets via various cytokines, including interleukin-6 (IL-6, 16)." (PMID 32375852, 2020). "Our qPCR data suggest that local inflammation was increased in the hearts of tumor-bearing mice, as demonstrated by the increase in relative transcript levels of IL-6 and MIP-2 transcription." (PMID 32722688, 2020). "Other pleiotropic cytokines that share downstream signaling pathways with IL-23, like IL-6, are also induced through immunometabolic interactions in the tumor microenvironment." (PMID 32193527, 2020). "Several cells and cytokines have been reported to be involved in immunosuppression, such as tumor-associated macrophages, cancer-associated fibroblasts, myeloid-derived suppressor cells, regulatory T cells, TGF-β, IL-6, and interferon." (PMID 31907020, 2020). "STAT3 expressed by the tumor cells further enhances IL-6 secretion by the myeloid cells via increased expression of NF-κB in these inflammatory cells, thus creating a positive feedback loop." (PMID 33143283, 2020). "Cooperativity between CCR5-related pathways and other elements was revealed when maraviroc—that did not act alone to prevent tumor cell survival—potentiated the effect of IL-6-directed inhibition in reducing tumor cell proliferation." (PMID 32582148, 2020). "Interleukin-6 promotes tumour growth by inducing multiple signalling pathways, including proliferation, angiogenesis and metabolism." (PMID 33028394, 2020). "In CRC, IL-6 and TNFα participate in most steps of cancer progression, including tumor initiation, proliferation, migration, and angiogenesis." (PMID 32317968, 2020). "As expected, DCs responded to bacteria treated tumor cells with significant increase in cytokines secretion, including IL-1β, IL-6, MCP-1, and TNF-α." (PMID 33643911, 2020). "This association of CCF‐activated STING with inflammatory gene expression (IL‐1A/B, IL‐6, IL‐8) was supported by clinical tumor expression data." (PMID 32918364, 2020). "Evidence suggests that inflammatory signals from the macroenvironment and the tumour microenvironment promotes and sustains oncogenesis through the production and release of pro-survival factors such as interleukin-6 (IL-6)." (PMID 32331320, 2020). "HA is well-known for its promotion of cellular viability which is thought to be via the CD44 receptor and the IL6 pathway; this effect has also been seen in tumor cells." (PMID 32974357, 2020). "The survival benefits of STAT3 inhibition have been shown in a GL261 model, where the expression of cytokines promoting tumour growth, such as IL‐10 and IL‐6, was blocked." (PMID 32567735, 2020).